LAG3 (lymphocyte activating 3)
Diseases named in the same sentence as LAG3 in open-access papers (continued):
Sharing a sentence is not in itself a finding about the gene and the disease.
tumor (continued). "LAG-3 is upregulated in tumor-infiltrating Treg and experiments with anti-LAG-3 mAb demonstrated that functional LAG-3 is required for maximal Treg suppressive function." (PMID 23986759, 2013). "Preclinical data show that blockade of LAG-3 or Tim-3, or ligation of 4-1BB, can potently augment immune-mediated tumor rejection in vivo." (PMID 24829752, 2013). "Moreover, LAG-3 contributes to an immunosuppressive environment via inducing IL-6 secretion and impairing IFN-α production in tumor-associated pDCs, and promotes monocytes to release CCL2, resulting in the recruitment of MDSCs." (PMID 41486149, 2026). "Although no individual T cell surface marker is an accurate predictor of tumour-antigen specificity, multiple studies suggest that expression of multiple IhRs such as PD-1, LAG-3, TIM-3, the integrin protein CD103 and oligoclonality of CD8+ T cells are associated with tumour-specificity." (PMID 41574275, 2026). "Checkpoint inhibitors targeting PD-1 have shown unprecedented efficacy in some cancer patients; however, co-expression of the immune-checkpoint LAG-3 by tumor infiltrating lymphocytes (TILs) might hinder such efficacy." (PMID 42284551, 2026). "To explore the importance of metabolism on the features of iNKT cells, we simultaneously investigated the metabolic profiles of iNKT cells and the expression of an activation marker (CD69) and ICPs (PD1 and LAG3), whose expression was highly modulated in tumor-infiltrating iNKT cells." (PMID 41562072, 2025). "This suggests that LAG3-expressing CD8 + T cells may exert a more potent anti-tumor immune response." (PMID 40411616, 2025). "Notably, high proportions of LAG3-expressing tumor-infiltrating iNKT cells were highly predictive of shorter OS." (PMID 41562072, 2025). "However, in the tumor microenvironment, persistent antigen exposure leads to LAG-3 over-expression, which contributes to T cell exhaustion and impaired immune function." (PMID 40565041, 2025). "A high LAG3 level facilitates tumor development by suppressing the immune microenvironment." (PMID 39720765, 2025). "Increased expression of LAG-3 has been found in ESCC tumor tissues compared to normal tissues." (PMID 40075698, 2025). "Notably, LAG‐3 expression in tumor‐infiltrating lymphocytes has been correlated with LDH levels and bone marrow involvement in prior studies." (PMID 40091778, 2025). "The immune environment of ccRCC is distinct, marked by a high presence of immune cells like CD8+ T cells, regulatory T cells (Tregs), and tumor-associated macrophages (TAMs), alongside increased expression of immune checkpoint molecules such as CTLA4, PD-1, and LAG3." (PMID 40243888, 2025). "This may result from the inherent tumour heterogeneity in PD-L1 and LAG-3 expression, which is often difficult to capture in small biopsy specimens." (PMID 40265075, 2025). "By targeting two clinically relevant immune checkpoints, i.e. LAG-3 and PD-L1, we successfully prevented early-onset tumor development in the preclinical Msh2loxP/loxP mouse model, significantly prolonging overall survival following repetitive low-dose anti-PD-L1 or anti-LAG-3 administration." (PMID 40674934, 2025). "In tumor regions where PD-1 is either blocked or PD-1 receptors are absent, Galectin-3 (encoded by LGALS3), produced by both tumor cells and macrophages, can interact with LAG3 on T cell surfaces to suppress IFN-γ secretion and induce T cell apoptosis." (PMID 40411616, 2025). "Additionally, LAG-3-targeted PET imaging is an effective noninvasive method for visualizing the shift in the tumor immune phenotype from “immunosuppressive” to “hot”." (PMID 40796887, 2025). "A recent study found that CD8+ T cells deficient in both PD-1 and LAG-3 exhibited enhanced tumor clearance and improved long-term survival compared to those lacking either PD-1 or LAG-3 alone." (PMID 40255905, 2025).
tumor (continued). "Also, inhibitory signals such as PD-1, CTLA-4, TIM-3, and LAG-3 are released, limiting T cell effector functions in peripheral tissues and tumor microenvironments and contributing to the maintenance of T cell anergy and exhaustion." (PMID 40728994, 2025). "Furthermore, when combined with an anti-LAG-3 mAb, triple immunotherapy was shown to be more effective than monotherapy or dual immunotherapy in inhibiting tumor growth." (PMID 40796887, 2025). "Moreover, it was shown that chronic tumor antigen stimulation leads to persistent overexpression of LAG3 on CD8+ tumor antigen-specific T cells, leading to their functional exhaustion." (PMID 40484866, 2025). "In addition to LAG3, two other important checkpoint molecules expressed by tumor cells, namely, the PD-L1 ligand (CD274) and its paralog PDCD1LG2, were significantly decreased in the high-risk groups." (PMID 40302936, 2025). "The quantification analysis revealed that LAG‐3+ A549 tumors possessed an apparently higher tumor signal than LAG‐3− A549 or H1975 tumors at 24 h post‐injection, e.g., 5.7 ± 0.9 vs 3.1 ± 1.0 %ID/cc (ROI; p < 0.05) and 6.5 ± 0.3 vs 3.0 ± 1.7 (T/M ratio; p < 0.05)." (PMID 39513410, 2025). "New therapies are being developed to disrupt these suppressive interactions, such as antibodies blocking other checkpoint pairs like TIM-3 and LAG3, or drugs reprogramming macrophage-tumor cell crosstalk like blocking CSF1-CSF1R signaling that recruits tumor-associated macrophages." (PMID 41425696, 2025). "Notably, tebentafusp-induced T-cell activation is associated with upregulation of immune checkpoints, particularly LAG3, in both skin and tumor infiltrates." (PMID 41170451, 2025). "Additionally, LAG-3 is expressed by regulatory T cells in the tumor microenvironment, contributing to their suppressive activities." (PMID 40234667, 2025). "Notably, researchers found that tumor-interacting CD4+ T cells showed higher LAG3 expression than CD8+ T cells and LAG3 showed strong binding affinity for MHC-II." (PMID 41425696, 2025). "In addition, we assessed the expression of PD-1 and LAG-3 exhaustion markers in a hypofunction induction assay by repetitively exposing T cells to tumor cells." (PMID 40433387, 2025). "In the Sa1N tumor model, LAG3/PD1 blockade resulted in 70% of the animals being tumor-free." (PMID 40761795, 2025). "Tumor gene expression profiling revealed that both type I and II IFN signaling associated with disease progression and higher expression of T cell exhaustion markers, including TIM3 and LAG3." (PMID 40536814, 2025). "In the high-risk group, we observed a substantial upregulation of several immune-suppressive and regulatory molecules, including PD-L1 (CD274), CD276, TIM-3 (HAVCR2), LAG3, and TGFB1, all of which are associated with an immunosuppressive tumor microenvironment." (PMID 40959429, 2025). "TRM cells have the characteristics of long-term tissue residence and rapid response to antigen stimulation, and they highly express various inhibitory checkpoint molecules (such as PD-1, CTLA-4, and LAG-3), playing an important role in anti-tumor immunity such as melanoma." (PMID 40821806, 2025). "In this study, we found that treatment with anti-LAG-3 mAb in the “hot Hepa1-6 tumors” could yield additional therapeutic effects, leading to a reduction in tumor volume and prolonged survival time compared with monotherapy or dual combination immunotherapy." (PMID 40796887, 2025). "Furthermore, the dual blockade of PD-1 and LAG3 restored T-cell function across ccRCC, sarcomatoid-differentiated ccRCC, and chRCC tumor samples." (PMID 39858107, 2025). "In addition, the upregulation of PD-1 and LAG3 after tumor encounter was more pronounced in SKM-W218-28z CAR-T cells than in SKM-G4A-28z cells." (PMID 40308593, 2025). "Finally, the FGF/FGFR1/NOTCH1 within RB1 variant group has a remarkably high ratio of inner‐tumor CD8+ T cell infiltration, non‐exhausted T cells, exhausted TCD8+PD‐1+LAG3− cells, and TRMCD8+CD69+CD103+cells." (PMID 40001320, 2025).
tumor (continued). "FGL1 exhibits high affinity for LAG-3, and their interaction facilitates tumor immune escape." (PMID 40356928, 2025). "Furthermore, concurrent chemoradiotherapy (CCRT) appears to modify the local tumor microenvironment, possibly through cytokine-mediated mechanisms, leading to localized increases in LAG3 levels." (PMID 40411616, 2025). "The distinct expression patterns of B7-H3 and LAG3 in response to specific antigenic stimulation suggest that these molecules could be useful for detecting tumor-reactive T cells, thereby, enhancing the efficacy of adoptive T-cell therapies." (PMID 40070836, 2025). "Although more CD8 T cells were detected in tumors (not significant), these cells were characterized by significantly higher expression of exhaustion markers (such as EOMES and LAG3), indicating that tumor‐derived T cells had become exhausted during tumorigenesis." (PMID 40019403, 2025). "Additionally, in the cancer context, LAG-3 also binds fibrogen-like protein 1 (FGL1) released by cancer cells, galectin-3 on tumor and tumor-associated stroma cells, and LSECtin on tumor cells." (PMID 40075753, 2025). "A key factor appears to be the number of tumor-infiltrating lymphocytes (TILs) expressing programmed cell death type 1 (PD-1), lymphocyte activation gene 3 (LAG3), T-cell immunoreceptor with Ig and ITIM domains (TIGIT), and T-cell immunoglobulin and mucin domain 3 (TIM3) markers." (PMID 40573308, 2025). "LAG-3 inhibits anti-tumor Tc1 activity and contributes to their exhaustion." (PMID 40299510, 2025). "Moreover, we show that these EGFR‐high tumour cells overexpressed LGALS3, CD59, laminins (LAMB1 and LAMB3), PROS1 and so on that induced LAG3 and CD44 expression in the associated CD8+ T cells featuring an exhaustion state." (PMID 40621643, 2025). "Additionally, the targeting of alternative immune checkpoints such as TIM-3 and LAG-3 on tumor-specific CTL clones can further enhance eradication of tumor cells as demonstrated in GCs." (PMID 40948758, 2025). "However, the markedly elevated LAG-3 expression suggests potential exhaustion resulting from prolonged exposure to tumour antigens, indicating a dynamic transition from early activation to immune dysfunction." (PMID 40136700, 2025). "Similarly, the co-upregulation of PD-1 and LAG-3 on exhausted TILs has been observed in resistant tumours, and dual PD-1/LAG-3 inhibition can reinvigorate these cells." (PMID 40647497, 2025). "Our data suggest that anti-LAG3 antibodies may be worth examining to reinvigorate dysfunctional tumor-infiltrating iNKT cells." (PMID 41562072, 2025). "Elevated expression of LAG3 in PBMCs suggests that LAG3 could be contributing to the immune evasion mechanisms employed by the tumor." (PMID 40484866, 2025). "This dual role of immunomodulation and intrinsic tumor suppression makes LAG3 distinct from PD‐1/CTLA‐4 and may explain the association of anti‐PD‐1 resistance with LAG3/FGL1 co‐expression." (PMID 41025546, 2025). "ATC accentuates this pattern: LAG-3, HAVCR2 and TIGIT co-expression defines a terminally dysfunctional CD8/γδ T-cell pool whose clonal diversity contracts in parallel with rising tumour mutational burden, suggesting neo-antigenic pressure but failed immune pruning." (PMID 40959084, 2025). "Blocking LAG-3 restores T-cell function and bolsters anti-tumor immunity." (PMID 40918452, 2025). "However, LAG-3 upregulation in tumor-infiltrating lymphocytes (TILs) in MHC II+ tumors has been shown to result in the failure of anti-PD-1 treatment following an initial response." (PMID 40075727, 2025). "Furthermore, the expression of the effector cytokine IFN‐γ was reduced, and several exhaustion markers, including Lag‐3, and Tim‐3, in tumor‐infiltrating γδ T cells, indicating the presence of an exhaustion‐like phenotype due to prolonged tumor burden." (PMID 39573933, 2025).
tumor (continued). "Non-recurrent/non-metastatic patients exhibited a higher density of tertiary lymphoid structures and closer proximity of CD20+ B cells, CD8+TIM3+, and CD8+LAG3+ cells to tumor cells compared to recurrent/metastatic patients, though the differences were not statistically significant." (PMID 40710213, 2025). "We combined flow cytometry, LEGENDplexTM immune profiling, and preoperative/postoperative serum cytokine analyses to determine checkpoint molecules (e.g., PD-1, TIM-3, LAG-3), immune cell profiles, as well as key markers on tumor cells (CD44, PD-L1, MHC class I/II)." (PMID 40860824, 2025). "The most abundant checkpoint ligand in terms of both absolute expression levels as well as being expressed by tumour cells and by different types of infiltrating myeloid cells is Lgals3/LGALS3, encoding GALECTIN-3, a ligand for the LAG-3 immune checkpoint receptor." (PMID 40473819, 2025). "Furthermore, increased LAG‐3 and PD‐1 expression in DLBCL tissues and peripheral blood CD8+ T cells has been linked to impaired tumor cell killing." (PMID 40091778, 2025). "Finally, the low baseline uptake of [68Ga]Ga-NOTA-C25 PET in the murine HCC models and the small tumor volume in the combination therapy group limited the accuracy of anti-LAG-3 mAb blockade on PET imaging." (PMID 40796887, 2025). "Notably, CD8+TIM3+ and CD8+LAG3+ cells were predominantly located in the tumor parenchyma of patients with recurrence/metastasis, whereas these cells were mainly distributed in the stromal regions of non-recurrent/non-metastatic patients." (PMID 40710213, 2025). "Importantly, when adding anti-TREM2 to PD1/LAG3 blockade, mice with a decrease in tumor volume had tumors less infiltrated by immunosuppressive macrophages, while still enriched in TCF+ PD1+ T cells and DCs compared to non responders." (PMID 40027748, 2025). "Interestingly, in the MC38 tumor model, LAG3/PD1 blockade resulted in 80% of the animals being tumor-free." (PMID 40761795, 2025). "Refinement of biomarker assessment—including co-expression of cytotoxic T-lymphocyte-associated protein 4 (CTLA-4), Lymphocyte Activation Gene 3 (LAG3), or tumor mutational burden (TMB) status—may help identify responders more accurately." (PMID 40881855, 2025). "Increased ORR and tumor shrinkage were observed at higher LAG-3 expression levels." (PMID 39751894, 2025). "We finally investigated whether targeting ribosomes could enhance ICB efficacy in the immunotherapeutic-resistance tumours by testing the combined impact of CX-5461 and anti-Lag3 in the CT26 model." (PMID 40646287, 2025). "Tumor-infiltrating effector CD8 T cells were identified as drivers of LAG3, TNFSF9, and HAVCR2 overexpression, which suggests effector CD8 TILs are activated and exhausted relative to circulating leukocytes, a finding that is consistent with reports across multiple human tumor types." (PMID 39932553, 2025). "Moreover, targeting ribosomes induces immune checkpoint expression (such as Lag3) and significantly sensitizes tumours to anti-Lag3 immunotherapy, eliciting potent tumour regression and deeper anti-tumour immune responses." (PMID 40646287, 2025). "LAG-3, a receptor protein belonging to the immunoglobulin superfamily, has been identified on activated T lymphocytes, playing a role in maintaining immune system homeostasis and promoting immune escape in the tumor microenvironment (TME)." (PMID 40277786, 2025). "Cytotoxic T-lymphocyte antigen 4 (CTLA-4), PD-1 and its ligand (PD-L1), and lymphocyte-activation gene 3 (LAG3) are expressed at higher levels in tumour-infiltrating lymphocytes, in the stroma and in the invasive front of MMRd tumours than in MMRp tumours (green panel)." (PMID 39271762, 2024). "The association between pretreatment tumor inflammation and the efficacy of BEMPEG + NIVO versus NIVO was evaluated using a four-gene signature, comprised of the following genes: CD274 (PD-L1), CD8A, LAG3, and STAT117 (see “Methods”)." (PMID 39025948, 2024).
tumor (continued). "Interestingly, despite their distinct classification and differences in the kinetics of LAG-3 + B cells, both 4T1 and E0771 tumor-bearing mice presented a similar composition when analyzing different cell markers within the LAG-3 + B cell compartment." (PMID 38773133, 2024). "The interaction between the FGL-1 in the cytoplasm of tumor cells interacts with LAG-3 on the surface of various lymphocyte cells and whether other molecular signals are involved in this process remain to be determined." (PMID 39252941, 2024). "It is unclear whether sLAG-3 by itself has its own signaling capacity in the context of tumor or whether it only serves as a biomarker for decreased LAG-3 activity." (PMID 39346924, 2024). "Elevated intra-tumor levels of TIM-3 have also been associated with the suppression of T-cell responses and reduced production of TNF-α, IFN-γ, and GrzB, especially when co-expressed with TIGIT, CTLA-4, or LAG-3." (PMID 38891056, 2024). "Furthermore, by measuring the ratio and mean fluorescent intensity (MFI) of PD-1, TIM-3, and LAG-3 in tumor-infiltrating CD8+ T cells, we found that Vegfb deletion did not affect the exhaustion state of CD8+ T cells." (PMID 39145452, 2024). "Previous studies revealed that in solid tumor patients, blocking LGALS3, a ligand for LAG3, in conjunction with immune approaches may promote anti-tumor immunity and boost tumor regression." (PMID 38643145, 2024). "Consequently, LAG-3 is often upregulated in various neoplasms, including melanoma, to mediate T-cell exhaustion." (PMID 38920700, 2024). "Of note, numerous studies have shown that tumor-infiltrating lymphocytes in GBM express LAG3." (PMID 39409893, 2024). "As a new target, LAG-3 has excellent potential in tumor immunotherapy." (PMID 38919624, 2024). "Notably, tumor-infiltrating TCPTP deficient OT-1 T cells have been shown to express reduced levels of exhaustion markers, PD-1 and LAG-3 during the late tumor development stages." (PMID 38707187, 2024). "LAG-3 and PD-1 have synergistic effects on the immunosuppression and escape of tumor cells." (PMID 39252941, 2024). "LAG-3 in combination with the typical inhibitory immune checkpoint PD-1/PD-L1 can co-mediate immune homeostasis, eliminate autoimmune diseases, and enhance tumor-induced tolerance." (PMID 38177102, 2024). "Another tool to repress antitumor immune responses is the expression of immunomodulatory proteins like programmed cell death protein 1 (PD-1), cytotoxic T lymphocyte associated protein 4 (CTLA-4) and lymphocyte activation gene 3 (LAG-3) or their respective ligands in the tumor microenvironment." (PMID 39075115, 2024). "LAG-3 is coexpressed with PD-1 on tumor-infiltrating lymphocytes, and preclinical evidence suggests that dual blockade of LAG-3 and PD-1 may enhance antitumor immune activity." (PMID 39422598, 2024). "Consequently, LAG3 blockade was found to enhance anti-tumor immunity and complement other immunotherapeutic approaches via a distinct mechanism involving the inhibition of cell cycle progression." (PMID 38617537, 2024). "For example, combining LAG-3 inhibitors with TIL therapy or bispecific antibodies could potentially enhance the anti-tumor efficacy by engaging different aspects of the immune system." (PMID 39743998, 2024). "In addition, we found a higher proportion of FGFBP2+ NK cells, CTLA4+ T cells, and a lower proportion of LAG3+ T cells in tumor tissues compared to normal tissues." (PMID 38604154, 2024). "FGL-1 is another ligand for LAG-3, expressed in hepatocytes, tumor cells, and some immune cells." (PMID 39660130, 2024). "Additionally, the combination of anti-cytotoxic T-lymphocyte-associated protein 4 (CTLA4) or anti-lymphocyte activation gene 3 (LAG3) with anti-PD1 antibodies has further increased tumor response rates through unleashing potent immune effector mechanisms." (PMID 38473216, 2024).